TRAJ21 (T cell receptor alpha joining 21)
Gene: T-cell receptor joining (J) gene on chromosome 14 (22,523,600 to 22,523,654, forward strand). Ensembl gene ENSG00000211868.
Diseases named in the same sentence as TRAJ21 in open-access papers:
TRAJ21 is named in the same sentence as 1 disease in open-access papers, as found by Europe PMC text mining. Sharing a sentence is not in itself a finding about the gene and the disease. The quoted sentences say what the papers report.
tumour (1 paper, 2018). "Here we show that the structures of two distinct TCRs (TRAV4+TRAJ21+-TRBV28+TRBJ2-3+ and TRAV4+TRAJ8+-TRBV9+TRBJ2-1+), originating from a polyclonal T-cell repertoire, bind to HLA-B*07:02, presenting a 13-amino-acid-long tumour-associated peptide, NY-ESO-160–72." (PMID 29531227, 2018).